Y_RNA (Y RNA )
Gene: Miscellaneous RNA gene on chromosome 6 (121,378,797 to 121,378,898, reverse strand). Ensembl gene ENSG00000207403.
Homologues: Orthologues: chimpanzee Y_RNA (99% identical), macaque Y_RNA (95% identical). Paralogues in human: Y_RNA (89% identical), Y_RNA (88% identical), RNY3 (87% identical), Y_RNA (87% identical), RNY3P1 (86% identical), Y_RNA (86% identical), Y_RNA (85% identical), Y_RNA (84% identical), Y_RNA (83% identical), RNY3P14 (82% identical), RNY3P4 (82% identical), Y_RNA (82% identical), and 96 more.